TNF (tumor necrosis factor)
Diseases named in the same sentence as TNF in open-access papers (continued):
Sharing a sentence is not in itself a finding about the gene and the disease.
Cachexia (continued). "Inflammatory cytokines, such as tumor necrosis factor-α (TNF-α), interleukin-6 (IL-6), and interferon-γ (IFN-γ), trigger a local “cachexia” response in adipocytes in which the lipid phase of adipose tissue decreases and the aqueous phase increases." (PMID 36640208, 2023). "The searches for IL-1β, IL-6, TNF, and JAK were based on reports that these were involved in cancer cachexia syndromes." (PMID 36358681, 2022). "The separate stimulation of TNF and IL-1β promoted the secretion of LIF and IL-6 in a cachexia study with tumor-bearing mice, resulting in a synergistic effect." (PMID 35740622, 2022). "It is known that proinflammatory cytokines such as TNF-α, IL-6, IL-1, and IFN-γ are involved in cachexia mechanisms found in experimental animals." (PMID 35097133, 2022). "Proinflammatory cytokines such as IL-6, TNF-α, and LIF have been identified to lead to muscle wasting in cachexia." (PMID 35740622, 2022). "Several pro-inflammatory cytokines such as TNF, IL1, IL6, and IFN-γ are previously identified to be upregulated in cachexia, and be able to stimulate the catabolic processes in experimental CAC models." (PMID 36376273, 2022). "The presence of myofibroblasts surrounding adipocytes was also noted in CRC, along with the increased pro- (e.g., TNF-α, IL-6, and IL-8) and anti-inflammatory cytokine (e.g., IL-5) content, as well as enhanced ECM protein synthesis due to cachexia." (PMID 33557173, 2021). "The inflammatory cytokines produced by tumor cells and leukocytes, including tumor necrosis factor alpha (TNF-α) and interleukin-1, interleukin-6, and interleukin-8 (IL-1, IL-6, and IL-8), are demonstrated to be the major drivers of cachexia." (PMID 34760698, 2021). "Recently, it was demonstrated that inflammatory cytokines, including interleukin 6 (IL-6) and tumor necrosis factor α (TNF-α) secreted by tumor cells and peripheral tissues, induce the development of cachexia." (PMID 33803685, 2021). "In conclusion, the role of CRC cells is related to the production of classic cachexia-inducing factors (e.g., PIF, IL-6 and IL-6R, TNF-α, IL-1β, IL-1R1, and LIF), as well as novel factors known as “cachexokines”." (PMID 33557173, 2021). "Its mechanisms are not completely clear, but participation of cytokines, contributing to the development of cachexia, such as TNF (Tumor Necrosis Factor) and IL-6 (Interleukin-6), is assumed." (PMID 33805156, 2021). "L-carnitine increased the gastrocnemius muscle (GM) weight in the CT26-bearing cachexia mouse model and the cross-sectional fiber area of the GM and myotube diameters of C2C12 cells treated with TNF-α." (PMID 34724970, 2021). "TNF-α, IL-6, and IL-8/CXCL8 were identified as the most important factors in CRC induced cachexia involving CAAs." (PMID 33557173, 2021). "In our previous study, we found that serum tumor necrosis factor (TNF)-α and high-mobility group box (HMGB)-1 were increased in cachexia patients." (PMID 33110478, 2020). "In the cachexia group, HMGB1 and TNFα increased by 1.8 times and 2.3 times, respectively, compared to those in the control group." (PMID 33110478, 2020). "We also evaluated expression of IL-6, TNF-α, IFN- γ, IL-1α, and IL-1β because these inflammatory cytokine are frequently observed in cachexia as well as fibrotic diseases." (PMID 32973293, 2020). "Although previous studies showed that plasma interleukin-6 (IL-6), tumor necrosis factor-α (TNF-α) and other inflammatory factors were significantly elevated in cancer cachexia patients, there were controversies among studies." (PMID 31788012, 2019). "Treatment with TNF inhibitors has been a successful strategy for several diseases such as RA, IBD, psoriasis, and cancer-related cachexia." (PMID 29725328, 2018). "A popular in vitro model of cachexia involves the treatment of C2C12 myotubes with IFNγ and TNFα (IT) for 72 h, recapitulating many facets of the cachectic muscle." (PMID 29849089, 2018).
Cachexia (continued). "Pro-inflammatory cytokines, such as TNF-α, IL-6, and IFN-γ, have been shown to be major drivers of cachexia as they promote tissue proteolysis and increase adipose tissue browning." (PMID 30081609, 2018). "We thereby measured serum levels of TNFα, IL-6 and IL-1β in LLC tumor-bearing mice during the development of cachexia on days 0, 7, 14 and 21 of tumor implant as well as that of Hsp70/90 and EVs." (PMID 28928431, 2017). "Plasma levels of several pro-inflammatory cytokines including TNFα, IL-6, IL-1 and IFN-γ in circulation have been assessed as markers of cachexia." (PMID 28177923, 2017). "Inflammatory cytokines derived from cancer cells and host immune cells, including interleukin (IL)-1, IL-6, tumor necrosis factor (TNF)-α, and leukemia inhibitory factor (LIF), are involved in the development of cancer anorexia-cachexia." (PMID 28249026, 2017). "We found that serum TNFα and IL-6 levels were elevated in wild-type LLC tumor-bearing mice that developed cachexia, while IL-1β level remained unchanged." (PMID 28536426, 2017). "On the other hand, in a study of the pathophysiology of cachexia in patients with prostate cancer, a serum cytokinome profile of 10 biomarkers (IL-1β, IL-2, IL-4, IL-5, IL-6, IL-8, IL-10, IL-12, IFN-γ, and TNF-α) was evaluated." (PMID 28050120, 2016). "Elevated levels of tumor necrosis factor-α (TNF-α), interleukin-6 (IL-6), and PIF were reported in biological fluids (e.g., blood and urine) of patients experiencing cachexia." (PMID 27642498, 2016). "COPD whereas an improved physical performance of TNF-α inhibition has been indicated in COPD patients with severe disease and cachexia." (PMID 25155252, 2014). "Increased production of TNF-α and IL-6 accompanied by insufficient levels of GSH can generate excess free radicals that may be disadvantageous to the host because they not only cause acute-phase events, such as fever, but also mediate cachexia, hemorrhagic necrosis, and lethal shock." (PMID 24312131, 2013). "Sophocarpine and matrine inhibit the production of IL-6 and TNF-α by the murine macrophage cell line, RAW264.7, and significantly attenuate the experimental cachexia induced by C26 adenocarcinoma in mice." (PMID 23326296, 2012). "This is a particularly attractive theory regarding Tumor Necrosis Factor alpha (TNF-α) and the development of cachexia in COPD." (PMID 22708547, 2012). "Recently, the induction of iNOS expression by TNFα was demonstrated in human cancer and AIDS patients suffering from cachexia." (PMID 21832306, 2011). "The lack of efficacy of TNFα-neutralizing agents in clinical trials targeting cachexia, such as the monoclonal antibody infliximab and the TNF receptor fusion protein etanercept, further supports the translational relevance of our screening system." (PMID 40283883, 2025). "In the case of cancer cachexia, LIF acts in concert with a number of other catabolic factors (IL-6, TNF-α, GDF15, etc.)that may amplify signals of muscle-wasting." (PMID 40869331, 2025). "Furthermore, several molecular signatures observed in the medial basal hypothalamus during cachexia are also found in the peripheral tumour microenvironment, such as CCR1+ macrophages expressing TNF, IL-1β, and IL-6." (PMID 40362192, 2025). "In addition, several proinflammatory factors, such as TNFα, IL-1β, and IL-6, are increased in WAT during cachexia, as a result of both adipocyte secretion and immune cell infiltration." (PMID 41373779, 2025). "Based on these findings, we propose that ACT may exert its anti-cachexia effects through the regulation of inflammatory response and energy metabolism via multiple targets, including CYP3A4, CYP19A1, CYP2E1, TNF, BCL-2, RYR2, and ATP2A1." (PMID 39872045, 2024). "The pathway of NF-κB, which is activated by the TNF-α/TAK-1 signaling, may play an important role in cachexia." (PMID 38334644, 2024).
Cachexia (continued). "To evaluate local inflammation in skeletal muscle from PDAC patients with or without cachexia, we performed qRT‐PCR to examine mRNA expression of inflammatory cytokines tumour necrosis factor‐alpha (TNF‐α), interleukin‐6 (IL‐6), and interleukin‐1beta (IL‐1β)." (PMID 38725139, 2024). "Similarly, using CSS scores, the current study found cachexia to be significantly related to CRP, IL-6, IL-8 and TNFα." (PMID 37906352, 2023). "Serum TNF-α level was not significantly different between PC patients with and without cachexia (P = 0.438) and did not correlate with the percentage of weight loss (r = 0.09, P = 0.294)." (PMID 37280516, 2023). "Studies have confirmed that TNF-α and IFN-γ are essential cachexia mediators." (PMID 35740622, 2022). "IL-1α, TNF, IL-8, and IL-10 were significantly elevated in cachexia patients but IL-1β and IL-6 were not significantly elevated in the cachexia patients." (PMID 36358681, 2022). "The cachexia that ensues from T. cruzi infection did not occur in Il-1r−/− mice, an unexpected finding, since it has been solely credited to TNF signaling." (PMID 36341442, 2022). "Levels of Interleukin-6 (IL-6), Tumor Necrosis Factor α (TNF-α), and Interferon γ (IFNγ) correlated with bacterial translocation in patients with cachexia and these inflammatory cytokines may drive myocyte cell death." (PMID 36698827, 2022). "Circulating leptin levels were found independent of the TNF-α system, and they were regulated physiologically even in the presence of cachexia in patients with COPD." (PMID 36139468, 2022). "Extensive investigations into the binding signature of cA2 and the blocked activities showed that it bound and neutralized soluble and membrane TNF but not lymphotoxins and inhibited cachexia and TNF-induced mortality." (PMID 36358688, 2022). "In mouse models, the administration of TNF-α has been shown to induce cachexia, however TNF inhibition alone was not sufficient to reverse the cachexia phenotype, indicating the complex underlying pathophysiology of the syndrome." (PMID 35743911, 2022). "Promotes tumor progression, invasion, and migration andmediates apoptosis.Higher miR-155 contributes to cachexia through the inhibition of negative feedback loops of SOCS1.miR-155 mediates TNF-Α showing a pro-inflammatory effect." (PMID 36465353, 2022). "In recent years, research has mainly focused on the role of pro-inflammatory cytokines, such as interleukin-6 (IL-6), interleukin-1 (IL-1), tumor necrosis factor alpha (TNF-α), and interferon gamma (IFN-γ), and confirmed their involvement in the pathogenesis of cachexia." (PMID 34830921, 2021). "Hence, the presence of activated myofibroblasts surrounding adipocytes was confirmed, along with the increased of pro-inflammatory cytokine content (e.g., TNF-α, IL-6, and IL-8), with enhanced ECM protein synthesis due to cachexia." (PMID 33557173, 2021). "In clinical trials, the neutralization of circulating IL-6 or TNFα have not proven useful to counteract CC, indicating that other factors are involved in cachexia." (PMID 33255345, 2020). "Tumor necrosis factor-alpha (TNF-α), interleukin 1 (IL-1), interleukin 6 (IL-6) and interferon-gamma (IFN-γ) are the main cytokines that are thought to be involved in the evolvement of cachexia, in general." (PMID 32655411, 2020). "In addition, it is known that TNF-α may not only enhance inflammatory events within the respiratory tract but also plays a role in the development of systemic inflammation; one of the manifestations of which is the development of cachexia in some patients with severe COPD." (PMID 32733164, 2020). "In the four cachexia cytokines, T cell expressed IFN-γ, TNF-α and IL-637–41." (PMID 32139788, 2020). "While the original rationale for anti-TNF treatment was to intervene in the lung pathology, more recent insights suggest that specific groups of patients, in particular COPD patients with cachexia may benefit from TNF-blocking agents." (PMID 33329046, 2020).
Cachexia (continued). "One example regards tumor necrosis factor-alpha (TNFα) and TNF-weak inducer of apoptosis (TWEAK), two pro-inflammatory cytokines known to induce skeletal muscle wasting under conditions of experimental cachexia through indirect destabilization and suppression of MyoD." (PMID 33330108, 2020). "As a symptom of cancer cachexia, CRF is induced by various mediating factors, such as cytokines (tumor necrosis factor α (TNF-α), interleukin 1 (IL-1), IL-6, and interferon-γ (INF-γ)), hormones (insulin, glucagon, leptin, ghrelin, and adiponectin), and neuropeptide-Y." (PMID 31323874, 2019). "In cancer cachexia patients, these circulating levels of TNF-α are elevated, but not correlated with clinical markers of cachexia." (PMID 30094378, 2018). "Accordingly, it seems that the near to normal weight achieved after bariatric surgery reflects a cachexia-like state rather than a healthy lean phenotype, particularly indicated by the extensive upregulation of TNF expression in the post-obese group." (PMID 27900559, 2017). "Taken together, this work demonstrates that different pro‐cachectic inducers (i.e. IL‐6 and IFNγ/TNFα) activate STAT3 signaling independently and that this signaling can collaborate with the NF‐κB pathway to induce cachexia through activation of target genes, like iNOS." (PMID 28264935, 2017). "Similar results were found upon treatment of cachectic rodents with anti-myostatin inhibitors, where signs of cachexia were reversed without affecting IL-6 or TNF-α plasma levels." (PMID 25460504, 2015). "In the 16 male patients, median levels of IL-6, TNF-α, and leptin at 6:30 AM didn't differ significantly between the cohorts with and without cachexia." (PMID 25411961, 2014). "Median levels of IL-6, TNF-α, and leptin at 6:30 AM didn't differ significantly between the cohorts with and without cachexia, and the observed trends in level fluctuations were similar to those previously reported." (PMID 25411961, 2014). "Receptors for TNF-α, also showed a much lower elevation, indicating that TNF-α signaling may not be as crucial as IL-6 signaling in this particular model of cachexia." (PMID 22361433, 2012). "Multivariately, high levels of TNF-α (but not CRP, IL-1ß or IL-6) significantly predicted loss of FFMI, however only in patients with established cachexia at entry." (PMID 22708547, 2012). "More importantly, some studies have shown higher systemic levels of TNF-α in COPD patients with cachexia compared with patients without cachexia." (PMID 22708547, 2012). "Taking into account that (a) TNF-α induces cachexia and (b) a lower weight is correlated with active RA, it could be hypothesized that IFX good responders are more likely to have a TNF-α-driven disease, leading to a lower BMI." (PMID 22584116, 2012). "The other cytokines we observed increased in C26 mice that might also play a role in muscle wasting include IL-6-family ligands such as LIF, as well as TNF-a, IFN-gamma, all of which can induce cachexia independently." (PMID 21799891, 2011). "In particular, tumor necrosis factor-α (henceforth referred to as TNF, in agreement with Clark) is a principal cytokine involved in the pathogenesis of muscular dystrophy and other disease states such as cachexia." (PMID 19440308, 2009). "In addition, serum levels of either S100A8, S100A9, or S100A8/A9 did not correlate with those of IL-6 or TNF-α in PC patients with cachexia (n = 80)." (PMID 37280516, 2023). "In contrast, higher TNF-α mRNA expression than in c20-bearing animals, both at tumor sites and in the spleens of c5-bearing mice, suggested that IL-6, not TNF-α, may be a key mediator of cachexia in this model." (PMID 33557173, 2021). "For example, the collaboration between STAT3 and NF-κB pathways has been shown to modulate IFN-γ/TNF-α-induced muscle wasting, suggesting that inflammatory signaling acts through integrated networks of downstream effectors, such as STAT3 and NF-κB to induce cachexia." (PMID 30081609, 2018).
Cachexia (continued). "A comprehensive review of clinical factors associated with cachexia showed little evidence for the association between serum TNF-α and weight loss in cancer, while several studies report an association of plasma IL-6 but not TNF-α with cachexia-associated wasting rather than cancer per se." (PMID 26508820, 2015). "It was hypothesized that cytokines as IL-1, IL-6, IFN-γ, TNF-α, brain-derived neurotrophic factor, MIC-1 may be involved in the cachexia process, in the imbalance which favors catabolism over anabolism, and in the neurologic and neuropsychiatric manifestations of the disease." (PMID 26337554, 2015). "Besides, median IL-6 and TNF-α levels appeared higher and leptin concentration appeared lower in the cachexia group, albeit without statistical significance." (PMID 25411961, 2014). "In agreement with the results of previous studies, median IL-6 and TNF-α levels in the cohort with cachexia were nearly double those in the cohort without, and leptin levels in the cohort with cachexia were around half those in the cohort without, albeit without statistical significance." (PMID 25411961, 2014). "The inhibitory effect of TTP in the regulation of TNF production first became obvious by significant cachexia in the TTP knockout mouse, which was explained by increased TNF concentrations and a feedback effect of TTP on TNF production by its binding to the ARE and destabilization of the TNF mRNA." (PMID 23028373, 2012). "These possibilities could have therapeutic consequences, since a TNF-α blocking agent presumably would not have an effect before cachexia was already developed if the first explanation was correct." (PMID 22708547, 2012). "However, the measured levels of TNF-α in BAL and blood correlate poorly, and some studies have not found higher levels of TNF-α in COPD patients with cachexia compared with patients without cachexia." (PMID 22708547, 2012). "Third, the patients who were cachectic at entry may have had a longer exposure to inflammation before entering the study, implying that the non-cachectic patients with high TNF-α levels will develop cachexia if followed longer." (PMID 22708547, 2012). "As a result under pro-inflammatory pressures, the inhibition of TACE will lead to increased levels of membrane-bound TNFα which could potentially stimulate some TNFα-mediated responses, not the least of which could be cachexia." (PMID 22852058, 2012). "Anti-TNF may reverse cachexia in CD patients, allowing them to survive without surgery." (PMID 36997863, 2023). "Taken together, changes in IL-6, TNF-α or other pro-inflammatory factors reported previously might be the consequences of the complex tumor-incited immunological responses mediating cachexia, whereas our results support that S100A8, S100A9 and S100A8/A9 are potential drivers of PC-induced cachexia." (PMID 37280516, 2023). "However, little evidence shows that anti TNF therapy is effective in cachexia in humans." (PMID 38282952, 2023). "However, serum TNF-α was positively associated with serum FFA in early- but not late-stage cancer cachexia, which suggests TNF-α may accelerate WAT lipolysis in early-stage cancer cachexia, with reduced effect in late-stage cachexia." (PMID 29338749, 2018). "However, weight loss occurred rapidly in IFNAR1−/− mice and therefore must be independent of IFN-I, perhaps occurring via TNF-α, which is known to contribute to cachexia and whose expression is increased by poly I:C and not significantly diminished in IFNAR1−/− mice." (PMID 25900439, 2015). "Therefore, anorexic effects mediated by TNF-α may not be central to cachexia." (PMID 41294666, 2025). "The modesty of spleen TNF-α changes in AIA, therefore, is consistent with the lack of a wasting syndrome in this model." (PMID 15899031, 2005).